FOXP3 (forkhead box P3)
Diseases named in the same sentence as FOXP3 in open-access papers (continued):
Sharing a sentence is not in itself a finding about the gene and the disease.
COVID-19 (continued). "Single-cell research revealed that FoxP3 expression was noticeably lower in severe COVID-19 patients, despite greater expression of CD25." (PMID 36992283, 2023). "For instance, it has been shown that severe COVID-19 patients had significantly fewer Tregs (CD3+ CD4+ CD25hi CD127lo FoxP3+) in their PBMCs." (PMID 36992283, 2023). "For that, we evaluated blood levels of CD25+, conventional Tregs (cTreg; CD25+Foxp3+), and unconventional Tregs (uTreg; CD25-Foxp3+) in COVID-19 patients with different severity." (PMID 37833265, 2023). "CD4+ Foxp3+ regulatory T cells (TREGS) are a central component of immune regulation, as humans are reliant on TREGS expressing Foxp3 gene, which has been extensively investigated in the context of cancer regulation and COVID-19." (PMID 36851285, 2023). "Severely infected patients with COVID-19 have shown unique Treg phenotype and increased expression of its characteristic transcription factor FoxP3." (PMID 36992283, 2023). "Prior to Treg-based treatment, it is important to thoroughly understand the continuous fluctuations of Tregs, especially their percentage, suppressive function, and FOXP3 stability during various phases of COVID-19." (PMID 36992283, 2023). "The median value of percentage of CD8+ Tregs (CD3+CD8+CD25+Foxp3+) among all patients with COVID-19 were higher than controls (0.4 [range, 0–4.2] vs. 0.3 [range, 0–1.5], Mann–Whitney U p = 0.001)." (PMID 36326397, 2022). "Of note, we saw an impressive reduction especially in CD4+CD25+FoxP3+ regulatory T cells (Tregs) in moderate/severe COVID-19 patients." (PMID 35265078, 2022). "So, it is meaningful to focus on the change of FOXP3+ Tregs in the COVID-19 patients with different severity." (PMID 35874688, 2022). "Another study found that severe COVID-19 patients had a higher number of Tregs with higher levels of FoxP3 expression than mild, recovered, or healthy controls." (PMID 36034704, 2022). "The T cells of patients with COVID-19 are highly activated, Foxp3 expression is inhibited, and hyperactive CD25+ Tregs proliferate quickly and die before they become fully functional Tregs." (PMID 36034704, 2022). "In mild COVID-19 patients, IL-2 drives differentiation into regulatory T cells (Tregs) expressing transcription factor forkhead box-p3 (FOXP3), which is crucial for maintaining immune tolerance and immune system homeostasis." (PMID 36499448, 2022). "A low number of Tregs and their factors FoxP3, IL-10, and TGF-β and inflammation can be regarded as the major causes of disease pathogenesis in patients with COVID-19." (PMID 36016311, 2022). "Significantly increased Foxp3+ Tregs were observed in 49 convalescents from Wuhan at ~ 112 days post-recovery; however, another study observed that CD25+Foxp3+ Tregs were significantly reduced 10 weeks after COVID-19." (PMID 35027067, 2022). "In COVID-19 patients, significant lower Treg frequencies, lower expression of forkhead box protein P3 (FoxP3), lower expression of transforming growth factor-β(TGF-β) and lower cytokine TGF-β secretion are observed compared to healthy control." (PMID 34757513, 2022). "The dynamic changes of Tregs including proportion, suppression function and FOXP3 stability under different COVID-19 stage should be well uncovered before Treg-based therapy." (PMID 35874688, 2022). "In this study, we found that during an active infection, patients with mild COVID-19 had a higher Tregs and FoxP3+ Tregs population." (PMID 36016311, 2022). "In severe COVID-19 patients, T cell expression of FOXP3 is repressed, likely due to high levels of pro-inflammatory cytokines, especially IL-6, which has emerged as a key inducer of the cytokine storm." (PMID 36499448, 2022). "Cytometric and transcriptomic profiling revealed a distinct Treg phenotype in severe COVID-19 patients, with an increase in Treg proportions and intracellular levels of the lineage-defining transcription factor FoxP3, correlating with poor outcomes." (PMID 34433692, 2021).
COVID-19 (continued). "It appears that severe COVID-19 entails a striking induction of Treg activation markers including FoxP3, KLRG1 and PD1 and a reduction of CD45RA, a marker of naïve Tregs." (PMID 34512643, 2021). "The expression levels of CD4, CD25 and FOXP3 showed a significant decrease in severe COVID-19 patients’ PBMC compared to controls (p < 0.0001, p = 0.01, p = 0.007, respectively) and CD patients (p < 0.0001 for all of them)." (PMID 34895167, 2021). "For example, it has been reported that Tregs (CD3+ CD4+ CD25hi CD127lo FoxP3+) in PBMCs were markedly decreased in severe COVID-19 patients 59-61." (PMID 33907514, 2021). "On the contrary, the relative level of CD4, CD25 and FOXP3 mRNA expression in COVID-19 patients was significantly lower than in controls (p < 0.0001, p = 0.01, p = 0.007, respectively)." (PMID 34895167, 2021). "In severe COVID-19 patients, T cells are highly activated but Foxp3 expression is inhibited, while hyperactivated CD25+ T cells proliferate and die rapidly before differentiating into Tregs." (PMID 34631206, 2021). "To decipher the functional consequences of FoxP3 overexpression in Tregs from severe COVID-19 patients, we generated 86 RNA-sequencing (RNA-seq) transcriptome profiles, passing quality thresholds, of blood Treg (CD4+CD25hiCD127lo) or Tconv (CD4+CD25−)." (PMID 34433692, 2021). "The expression level of CD4, CD25, and Foxp3 was significantly downregulated 5-, 2-, and 3-fold, respectively, among COVID-19 patients in comparison to healthy controls (P-value < 0.0001)." (PMID 33244382, 2020). "The results show a decrease in the mRNA expression levels of TCD4, CD25, and Foxp3 in COVID-19 patients." (PMID 33244382, 2020). "It has also been reported that reduced CD4+FoxP3+ Tregs are present in COVID-19, but an increased frequency of TIGIT+ Tregs at the time of hospital admission, which correlates with severity, suggesting that a robust suppressive activity is associated with fatal outcomes." (PMID 41488664, 2025). "However, other studies reported a significant decline in the frequency of T-regs in COVID-19 patients as well as a lower expression level of Foxp3 mRNA." (PMID 38139439, 2023). "Likewise, another recent observation found that the number, multiplication, and expression of certain proteins of CD25+ CD127+ FOXP3+ Tregs increased, along with their growing suppressive activity, in severely infected patients with COVID-19." (PMID 36992283, 2023). "Moreover, an increased gene expression level of LAG3 was detected in peripheral blood Foxp3+ Tregs15 and in lung autopsies of severely ill COVID-19 patients." (PMID 37833265, 2023). "In addition, it was also shown that all COVID-19 convalescent vs. healthy subjects have low levels of CD25+Foxp3+CD127- regulatory T cells." (PMID 37626620, 2023). "Other theories to explain the decreased amount of this cell subset in COVID-19 are the IL-6 induced transformation of regulatory T cells into Th17 effector cells and the hypoxia-induced degradation of Foxp3 through the activation of the hypoxia-inducible factor-1α." (PMID 36045688, 2022). "On the other hand, a recent study of the Tregs (CD4+ FoxP3+ CD25+) in PBMC of COVID-19 patients treated in intensive care units showed a significant decrease in Treg numbers and a similar decrease in the expression of FoxP3 mRNA and immunosuppressive cytokines (IL-10 and TGFβ)." (PMID 36362440, 2022). "Consistent with the ability of CD4+ T cells to regulate the recruitment and function of phagocytes in peripheral tissues, severe COVID-19 in adults have shown to be associated with changes in the function of two different CD4+ T cell profiles; FoxP3+ regulatory T cells (Tregs) and TH17 cells." (PMID 35663467, 2022). "Patients with severe COVID-19 may also see an increase in the degradation of FOXP3 proteins because the hypoxic lung environment activates HIF1A, which is involved in aerobic glycolysis." (PMID 37521843, 2022).
COVID-19 (continued). "Additionally, it has been reported that expression level of CD4+FoxP3+CD25+ was significantly decreased in COVID-19 patients, compared with healthy controls." (PMID 35497875, 2022). "Such as complement activation; COVID-19, thrombosis and anticoagulation; FOXP3 in COVID-19 was found in the COVID-19 cohort; meanwhile, COVID-19, thrombosis and anticoagulation; complement activation and Cells and molecules involved in local acute inflammatory response were found in the QIV cohort." (PMID 36275736, 2022). "Studies investigating fatal cases of COVID-19 found a profound dysfunction of Tregs in the lungs and pulmonary draining lymph nodes of autopsied patients, as indicated by lower FoxP3 expression, limited IL-10 production, and a paucity of FoxP3+ Tregs compared to surviving and non-COVID-19 controls." (PMID 36582234, 2022). "In addition, severe COVID-19 patients showed the transcriptional suppression of the expression of Forkhead Box P3 (FOXP3) and an impaired differentiation of Th17 cells compared to moderate COVID-19 patients." (PMID 36499533, 2022). "Therefore, small molecules targeting the PTMs or partner-interactions of FOXP3 have the potentiality to be developed into drugs for COVID-19 therapy." (PMID 35874688, 2022). "However, CD25+FoxP3+ Tregs were significantly decreased in convalescent COVID-19 patients, compared with healthy donors." (PMID 35497875, 2022). "Last, hypoxia in the lungs of severe COVID-19 patients can activate hypoxia-inducible factor-1α, which binds to Foxp3 and targets the proteasome for degradation, leading to the abrogation of Foxp3 autoregulatory transcriptional loop and thereby impeding the differentiation of Tregs." (PMID 34631206, 2021). "Moreover, a recent study reported that the proportion of Tregs (defined by CD3+ CD4+ CD25+ FoxP3+) and the levels of FoxP3 expression by Tregs were increased in COVID-19 patients, and that was correlated with poor outcome." (PMID 33907514, 2021). "In line with the cytometry, Tregs from severe COVID-19 patients showed higher FOXP3 expression." (PMID 34433692, 2021). "FoxP3+ Tregs are also elevated in several severe COVID-19 patients." (PMID 34512643, 2021). "Finally, exhaustion genes such as PDCD1/PD-1 or regulatory genes such as FOXP3 were under-expressed among COVID-19 compared to INFL or HTLY, mainly among TUBE early patients." (PMID 34135895, 2021). "We hypothesized that perturbations in FoxP3+ T regulatory cells (Treg), key enforcers of immune homeostasis, contribute to COVID-19 pathology." (PMID 34433692, 2021). "They concluded that increased levels of Th17, as well as reduced number of Treg cells and associated determinants such as FoxP3, IL10 and TGF-β might perform a leading role in elevating inflammation and pathogenesis of COVID-19." (PMID 33244382, 2020). "Firstly, we hypothesized that FOXP3 transcription was actively repressed by cytokines in the microenvironments in severe COVID-19 patients." (PMID 33178221, 2020). "Our findings indicated the expression profile analysis of CD4+ FoxP3+ CD25+ T cells could be a potential marker for the assessment of severity of COVID-19 patients." (PMID 33244382, 2020). "Therefore, under the inflammatory conditions brought on by COVID-19, high levels of IL-1, IL-6, and IL-23 may promote the downregulation of FOXP3, resulting in decreased functionality of Tregs." (PMID 36992283, 2023). "Additionally, recent research found that patients with COVID-19 had higher proportions of Tregs (characterized by the presence of CD3+ CD4+ CD25+ markers) and higher levels of FoxP3 expression by Tregs, which were associated with a poor prognosis of the disease." (PMID 36992283, 2023). "Thus, we assessed the impact of MDSCs on CD4 + CD25 + Foxp3 + T in HC and COVID-19 patients." (PMID 36581679, 2022).
COVID-19 (continued). "Therefore, NRP-1/FoxP3 is an important axis that regulates Treg cells’ function, prevents exaggerated immune response in COVID-19, and could be a possible prognostic factor for patients with severe COVID-19." (PMID 36009579, 2022). "Similarly, another study demonstrated that, in critical COVID-19 patients, the frequency, the proliferation as well as the protein abundance of FOXP3, CTLA-4, GITR and ICOS of CD25+ CD127− FOXP3+ Tregs enhanced, along with their increasing suppressive function." (PMID 35874688, 2022). "In this review, we mainly summarize the latest research focusing on the change of FOXP3+ Tregs in the COVID-19 patients, discuss the relationship between disease severity and number change of Tregs and speculate the potential role of FOXP3+ Tregs during SARS-CoV-2 infection." (PMID 35874688, 2022). "Therefore, severe COVID-19 entails a striking induction of FoxP3 expression in Tregs." (PMID 34433692, 2021). "In addition, FOXP3 transcription is transiently activated in T-cells of severe COVID-19 patients but may be repressed due to their unique metabolic states." (PMID 33178221, 2020). "Meanwhile, the correlation analysis of ICD-related DEGs and immune cell infiltration in severe COVID-19 showed that TLR4, PIK3CA, FOXP3, ENTPD1, CD4, CASP1 and BAX were significantly correlated with a variety of immune cell infiltration." (PMID 38600309, 2024). "WikiPathways Interferon type I signaling pathways WP585, FOXP3 in COVID-19 WP5063, COVID-19 adverse outcome pathway WP4891, STING pathway in Kawasaki-like disease and COVID-19 WP4961." (PMID 36913345, 2023). "The inflammatory condition due to COVID-19 disturbed the frequencies of the TIGIT+ and TIGIT- FOXP3+ T regulatory cell subsets." (PMID 37604833, 2023). "Although the diminished TIGIT+ and TIGIT− FOXP3+ T regulatory cells count in the blood of COVID-19 patients independently of their respiratory status, their proportion of both TIGIT+ and TIGIT− FOXP3+ T regulatory cells subsets were strongly disturbed." (PMID 37604833, 2023). "In our cohort, FoxP3, IFNγ-R1, and STAT5+ gene expressions of T cell populations were significantly upregulated in severe COVID-19 compared to mild patients." (PMID 37569646, 2023). "In PBMC generated from COVID-19 patients receiving ICU care, recent research looked at Tregs and discovered a sharp fall in the proportion of Tregs along with lower production of FoxP3 and inhibitory cytokines such as IL-10 and TGF-beta." (PMID 36992283, 2023). "More robust upregulation of mRNA expression for FoxP3, STAT5+, ROR alpha+, and IFNγ R1 was detected in severe COVID-19 patients compared to mild groups." (PMID 37569646, 2023). "Total CD4+CXCR5+ Tfh cells and ICOS+Foxp3-activated Tfh cells increased and ICOS+Foxp3+ Tfr cells decreased in COVID-19 patients, especially in diabetic patients and those with severe disease." (PMID 35286241, 2022). "The relative numbers of T and B cells, CD4+ T cells, CD8+ T cells, CD4+FoxP3+ T cells and the mean signals for PD-1, CD27 and CD45RO in T cells were similar between COVID-19 patient and control samples." (PMID 35251032, 2022). "Single-cell analysis of T-cells from COVID-19 patients revealed that CD4+ T-cells were activated with high expression of regulatory responses and CD25 as well as suppression of FOXP3 expression in severe COVID-19." (PMID 35763685, 2022). "In a recent study, decreased number of Tregs with a decreased expression of FoxP3 mRNA and immunosuppressive cytokines (IL-10 and TGFβ) was reported in PBMC derived from the COVID-19 patients treated in ICU." (PMID 34895167, 2021). "Due to lack of sufficient information about the expression levels of Tregs and its role in regulation of IL-6 cascade in COVID-19 patients, this study aimed to evaluate the expression level of IL-6 and CD4+ Foxp3+ CD25+T cells in COVID-19 patients." (PMID 33244382, 2020).
COVID-19 (continued). "Evaluating the expression level of CD4+ FoxP3+ CD25+ T cells and IL-6 in peripheral blood samples of hospitalized COVID-19 patients." (PMID 33244382, 2020). "In this study, we determined the mRNA expression of three key genes of T-helper subpopulations, i.e., FOXP3 (Treg), RORγt (Th17), and T-bet (Th1), in patients with COVID-19 and T2D who did or did not take metformin." (PMID 38400056, 2024). "Moreover, TBX21 and FOXP3, the main transcriptional factors for TH1 cells and TREG cells, respectively, have been found to be overexpressed in patients with poor outcomes in COVID-19." (PMID 38298642, 2024). "Analysis of regulatory T cells (Tregs) revealed decrement in percentage of CD4+ FoxP3+ T cells as well as in percentage of CD4+ IL-10 producing T cells (data not shown) in terminal stage of COVID-19." (PMID 37057213, 2023). "Indeed, a statistically significant upregulation of FoxP3, IFNγ-R1 (3-fold changes), and STAT5+ (2.5-fold changes) were observed in severe COVID-19 patients compared to mild groups (p < 0.0001) on day one of disease detection." (PMID 37569646, 2023). "Moreover, single-cell analysis in severe COVID-19 patients revealed that CD4+ T cells are hyperactivated, but Foxp3 expression is repressed." (PMID 37809093, 2023). "Moreover, activated CD4+ T cells in severe COVID-19 patients expressed higher levels of CD25, while suppressing the expression of FoxP3, resulting in a disrupted FoxP3-mediated mechanism in the lung." (PMID 35497875, 2022). "A lower frequency of CD4+CXCR5+ICOS+ Foxp3+ Tfr cells was found in the diabetic patients compared to controls (p = .01) and non-diabetic COVID-19 patients (p = .02)." (PMID 35286241, 2022). "The molecular mechanisms of Foxp3 expression and the antigen-specific response of CD4+ and CD8+ Treg cells in COVID-19 remain unclear." (PMID 36326397, 2022). "We observed that FoxP3- but not FoxP3+ CD4+ T cells from children with COVID-19 showed an increased expression of CD39 (p<0.05 and p<0.01 for non-severe and severe vs controls, respectively)." (PMID 35663467, 2022). "Interestingly, FoxP3, which improves the expansion of Treg cells’ function is severely downregulated in SARS-CoV-2 infection and coincides with COVID-19 severity." (PMID 36009579, 2022). "In severe COVID-19 patients, CD4+ T cells are hyperactivated, but Foxp3 expression is repressed." (PMID 34631206, 2021). "Among these, module M4 was almost exclusively composed of cell cycle-related transcripts, and strongly correlated with FoxP3 MFI, indicating that Tregs in COVID-19 patients are highly proliferative, plausibly a compensation for the lymphopenia in many severe patients." (PMID 34433692, 2021). "These CD25+ activated T-cells are likely to be short-lived and do not initiate FOXP3 transcription in severe COVID-19 patients, while they can differentiate into Tregs in moderate infections." (PMID 33178221, 2020). "Notably, those T-cells in severe COVID-19 patients highly expressed immunoregulatory receptors and CD25, whilst repressing the expression of FOXP3." (PMID 33178221, 2020). "Given that this last phase of pseudotime 1 (i.e. UMAP clusters 3 and 6) is dominated by CD4+ T-cells from severe patients, these results collectively support that FOXP3-mediated negative feedback on T-cell activation is defective in COVID-19 patients." (PMID 33178221, 2020). "Interestingly, we found higher CD3+CD4+CD25+FOXP3+CD39+ T cell frequency in unstimulated conditions in Mild Recovered volunteers who had not experienced musculoskeletal symptoms (arthralgia and myalgia) during acute COVID-19." (PMID 36969257, 2023). "One study found that Tregs in the lung of severe COVID-19 patients downregulated FoxP3 expression, and they were of a more activated rather than a suppressive phenotype, which could induce hyperinflammation and tissue damage." (PMID 35497875, 2022).